SVOPL (SVOP like)
Synonyms: MGC46715; SLC22B5
Tractability: Small molecule: it belongs to a druggable protein family. Antibody: UniProt predicts a signal peptide or a membrane-spanning region.
Gene: Protein-coding gene on chromosome 7 (138,594,285 to 138,701,382, reverse strand). Ensembl gene ENSG00000157703.
Subcellular location: Membrane
Gene Ontology:
Molecular function: transmembrane transporter activity
Biological process: transmembrane transport
Cellular component: membrane
Genetic constraint (gnomAD): Loss-of-function variants: 42 observed, 46.22 expected, observed/expected ratio (o/e) 0.91, 90% interval 0.71 to 1.17. The upper end of that interval is the gene's LOEUF score, 1.17, which puts it in group 5 of 6, group 1 being the genes least tolerant of losing a copy. Missense variants: 562 observed, 560.7 expected, observed/expected ratio (o/e) 1, 90% interval 0.94 to 1.08. Synonymous variants: 229 observed, 213.22 expected, observed/expected ratio (o/e) 1.07, 90% interval 0.96 to 1.2.
Homologues: Orthologues: chimpanzee SVOPL (98% identical), macaque SVOPL (97% identical), dog SVOPL (93% identical), pig SVOPL (92% identical), rabbit SVOPL (92% identical), mouse Svopl (92% identical), rat Svopl (91% identical), guinea pig SVOPL (75% identical), tropical clawed frog svopl (73% identical), zebrafish svopl (53% identical), Caenorhabditis elegans oct-1 (23% identical), Drosophila melanogaster Orct2 (23% identical), and 38 more. Paralogues in human: SVOP (38% identical), SLC22A7 (25% identical), SLC22A2 (24% identical), SLC22A6 (23% identical), SLC22A13 (23% identical), SLC22A15 (23% identical), SLC22A5 (22% identical), SLC22A4 (22% identical), SLC22A1 (21% identical), SLC22A3 (21% identical), SLC22A8 (21% identical), SLC22A14 (20% identical), and 10 more.
Diseases named in the same sentence as SVOPL in open-access papers:
SVOPL is named in the same sentence as 9 diseases in open-access papers, as found by Europe PMC text mining. Sharing a sentence is not in itself a finding about the gene and the disease. The quoted sentences say what the papers report.
colorectal cancer (3 papers, 2019 to 2025). A primary or metastatic malignant neoplasm that affects the colon or rectum. "Although research on SVOPL is limited, it may play a role in epigenetic dysregulation via allelic switching in colorectal cancer, while in breast cancer, higher expression appears linked to better treatment response and prognosis." (PMID 40282424, 2025). "The previous report has indicated allelic switching of SVOPL during colorectal cancer tumorigenesis." (PMID 36896338, 2023).
breast carcinoma (2 papers, 2023 to 2025). "A total of 16 genes were identified to be related to radiotherapy response, and low expression of SVOPL, EDAR, GSTA1, and ABCA13 was associated with poor overall survival and progression-free survival in breast cancer cases." (PMID 36896338, 2023). "Moreover, univariate cox analysis indicated that only four of them (SVOPL, EDAR, GSTA1, and ABCA13) were associated with the overall survival (OS) of breast cancer patients." (PMID 36896338, 2023). "In conclusion, we identified that SVOPL, EDAR, GSTA1, and ABCA13 are potential prognostic biomarkers of patients with breast cancer undergoing chemoradiotherapy." (PMID 36896338, 2023).
lung carcinoma (2 papers, 2019 to 2022). "Akin to SVOPL, the lung cancer proapoptotic factor BCL2L10 has been shown to display switching of the most abundantly expressed allele during tumorigenesis." (PMID 31093489, 2019).
Parkinson disease (1 paper, 2023). A progressive degenerative disorder of the central nervous system characterized by loss of dopamine producing neurons in the substantia nigra and the presence of Lewy bodies in the substantia nigra and locus coeruleus. "SVOPL has been found to be significant in Parkinson's disease by large‐scale whole‐exome sequencing, potentially deleterious in autosomal‐dominant lateral temporal epilepsy, and is associated with a super‐variant associated with brain connectivity." (PMID 37337823, 2023).
tumor (3 papers, 2019 to 2025). "We found that 14% of genes showed ASE in one or more cell lines and identified allelic switching of the potential cell survival genes DLX5, GRB10, and SVOPL on chromosome 7, whereby the most abundantly expressed allele in the normal tissue is the lowest expressed allele in the tumor and vice versa." (PMID 31093489, 2019). "Most samples showed strong downregulation of SVOPL, with a median 8-fold lower expression in the tumor compared to the normal sample, irrespective of allelic switching or any other change in the ASE status." (PMID 31093489, 2019). "Changing patterns of ASE in normal and tumor tissues suggests that ASE of DLX5 and SVOPL is not parent-of-origin-specific." (PMID 31093489, 2019).
cancer (2 papers, 2024 to 2025). A tumor composed of atypical neoplastic, often pleomorphic cells that invade other tissues. "SVOPL was the only gene found to be upregulated in cancer samples; all other dysregulated genes were downregulated in PTC tissue samples." (PMID 39408960, 2024).
SVOPL also shares sentences with these, for which no sentence is quoted: melanoma (1 paper); metastatic colorectal cancer (1); pancreatic cancer (1).